ENSG00000274458
Synonyms: LOC124900298
Gene: Small nucleolar RNA gene on chromosome 10 (36,438,661 to 36,438,788, forward strand). Ensembl gene ENSG00000274458.
Gene Ontology:
Biological process: RNA processing
Cellular component: nucleolus
Homologues: Paralogues in human: SNORA40B (96% identical), SNORA40 (93% identical), SNORA40C (91% identical).